IL4 (interleukin 4)
Diseases named in the same sentence as IL4 in open-access papers (continued):
Sharing a sentence is not in itself a finding about the gene and the disease.
influenza (continued). "The vehicle/vaccine group showed a delayed increase of IL-4 and IFN-γ producing influenza-specific cells although the levels of IL-4 secreting lymphocytes remained significantly lower than the EGFRI/vaccine group throughout the period of 14 days (p < 0.05)." (PMID 26227481, 2015). "SOCS1−/−IFN-γ−/− mice exhibited significantly decreased production of IL-6 and IL-10 at 7 dpi but increased IL-4, IL-5 and IL-13 levels in airways during influenza infection." (PMID 25500584, 2014). "We have previously evaluated the efficacy of membrane-anchored interleukins (IL) such as IL-2 and IL-4 co-presented as Cytokine-bearing Influenza Vaccines (CYT-IVACs) using a mouse model of influenza challenge." (PMID 24884849, 2014). "While an RSV infection of allergic animals results in enhanced Th2 cytokine production in the lungs, influenza respiratory challenge of AAD mice reduced lung IL-4, IL-5, and IL-13 expression." (PMID 23620814, 2013). "We also found that pulmonary iNKT cells from PD-L2−/− mice produce more IL-4 and IL-13 after influenza infection." (PMID 23555047, 2013). "Intrapulmonary influenza vaccine was capable of inducing IL-4-secreting T cells in the absence and presence of GPI-100 but the number of cells was significantly enhanced upon adjuvantation (p = 0.0033)." (PMID 23284901, 2012). "IL-4 Elispot assay revealed that plain influenza vaccine administered via the intramuscular route elicited Th2 cellular immune responses." (PMID 23284901, 2012). "Influenza infection alone also significantly increased IL-4 mRNA levels at day 8 and 14 p.i., while the DE exposure during influenza infection resulted in significantly higher IL-4 mRNA expression at days 1 and 4 p.i. compared to air exposed infected mice." (PMID 21092162, 2010). "Taken together, these data show that in OVA-sensitized mice, exposure to DEP prior to infection with influenza enhanced the expression of the TH2 cytokines IL-4 and IL-13 and their common receptor IL-4Rα." (PMID 19682371, 2009). "Blood feeding by D. andersoni pathogen-free nymphs or intradermal injection of salivary gland extracts programs influenza hemagglutinin influenza peptide specific TCR transgenic CD4+ T cells to express IL-4." (PMID 19814808, 2009). "Additionally, we observed decreased levels of eotaxin and IL‐4 during influenza infection alone in mice treated with baricitinib." (PMID 39921246, 2025). "We thus explored whether exogenous IL-4/IL-4 Ab complex could enhance the antiviral CD8 T cell response in influenza-infected mice." (PMID 38037190, 2023). "Exogenous IL-4 protected mice against lethal influenza infection." (PMID 38037190, 2023). "Upon blocking IL-4 intratumorally, all anti-tumor benefit of the influenza vaccine was eliminated." (PMID 38203396, 2023). "Thus, we turned to an alternative approach, quantifying influenza-specific cells following challenge, that we had previously used in assessing IFNγ and IL-4 producing T cells." (PMID 36038596, 2022). "In addition, the IFN-γ/IL-4 ratio and influenza antigen-specific total IgG production were significantly correlated." (PMID 35565949, 2022). "Using influenza as a model, live attenuated and killed inactivated influenza vaccines stimulate many shared pathways such as signaling of many interleukins (including IL-1, IL-4, IL-6, IL-13, IL-20, and IL-27), interferon signaling, MARK1 activation, and neutrophil degranulation." (PMID 33777032, 2021). "Moreover, it has been reported that geniposide can enhance the protective mechanism of anti-inflammation and immune regulation by enhancing the expression of IL-4 and IL-10, so as to play an anti-influenza role." (PMID 34867371, 2021). "Our curation indicates that the cytokine response induced by SARS-CoV-2 is different compared to other CRS-causing respiratory viruses, as SARS-CoV-2 does not always induce specific cytokines like other coronaviruses or influenza do, such as IL-2, IL-10, IL-4, or IL-5." (PMID 33732251, 2021).
influenza (continued). "Then we asked whether the early wave of IL-4 was necessary for the induction of B cell responses after influenza infection." (PMID 29249358, 2018). "However, the percentage of GFP+ NKT cells peaks up to 60% to 80% after 3 days of infection, indicating that influenza infection rapidly induces IL-4 production by NKT cells." (PMID 29249358, 2018). "Taken together, our results indicate that influenza infection triggers two spatiotemporally divergent waves of IL-4: an early wave, mainly produced by NKT cells and restricted to the periphery of B cell follicles, and a late one, produced by germinal center-resident TfH cells." (PMID 29249358, 2018). "Here, we tested whether STAT6 signaling is altered due to increased IL-4 levels in Stat2−/− mice during influenza-bacterial super-infection." (PMID 30337919, 2018). "Interestingly, flow cytometry analysis of lymph nodes from influenza-infected mice revealed that 80% of IL-4 GFP+ NKT cells express CXCR3, whereas only 30% of IL-4 GFP− NKT cells express this marker." (PMID 29249358, 2018). "Although IL-2, IL-4, and IL-17A may be involved in the pathogenesis of bronchial asthma and influenza infection, they were undetectable in the BAL fluid from mice in this study." (PMID 28831046, 2017). "In addition, IFN-λ increases influenza-induced Th1 cytokines (IFN-γ, IL6), whereas influenza-induced Th2 cytokines decrease (IL4, IL5, IL9, IL13)." (PMID 28293236, 2017). "Therefore, it is possible that T helper cell-independent IL-4 production is beneficial to the resolution of pathological changes resulting from influenza infection." (PMID 25500584, 2014). "However, the tetanus- and influenza-specific 2+γ- populations generated substantial amounts of IL-4 after culture in Th2 conditions." (PMID 24788814, 2014). "We observed polarization of CD1c+ DC response to Gardasil (HPV), IL-4 DCs response to Fluzone (influenza) and monocyte response to Pneumovax (pneumococcus), suggesting that responses to different vaccines may be mediated through unique APC subsets." (PMID 25335753, 2014). "Interestingly, in our transfer system PD-L1−/−-derived iNKT cells produced high levels of interferon-gamma whereas PD-L2−/−-derived iNKT cells produced high amounts of interleukin-4 and 13 suggesting a role for these cytokines in sensitivity to influenza." (PMID 23555047, 2013). "In addition, IL-4 was shown to reduce the cellular cytotoxicity in response to influenza infection, however additional studies are needed to elucidate the role of IL-4 on NK cell responses in the course of influenza infection." (PMID 33815404, 2021). "We found that direct influenza infection of monocytes and monocytes cultured with supernatants from virally infected lung epithelial cells induce distinct DC subsets compared with influenza infection of artificially generated IL-4-treated DCs and IFN-treated DCs." (PMID 30192848, 2018). "Furthermore, these analyses indicate that an early pre-TfH wave of NKT cells and IL-4 might be conserved upon influenza and Zika virus infection in mice and primates, respectively." (PMID 29249358, 2018). "Further, the IFN-γ mRNA levels were significantly higher (p < 0.05) compared to IL-4 and IL-10 mRNA levels, suggesting that Salmonella based vaccines have potential to skew the immune response toward Th1 type, which is important for the clearance of influenza infections." (PMID 28555133, 2017). "IL‐6 KO mice have a similar inflammatory cytokine profile to WT mice during post‐influenza MRSA pneumonia, including GM‐CSF, RANTES, TNFα, IFNγ, and IL‐4." (PMID 39921246, 2025). "We therefore measured the levels of several cytokines, including the pro-inflammatory TNF, IL-1β, IL-6, and IFN-γ, as well as IL-4, IL-10, IL-17A, and IL-22, in BAL samples from mice 5 days after influenza challenge." (PMID 40612502, 2025).
influenza (continued). "Furthermore, transcription of the Cxcl10 gene, which encodes the principal CXCR3 ligand in influenza-infected lungs, was not affected by IL-4C, suggesting that IL-4-driven CXCR3 upregulation in both CD44hi and CD44low CD8 T cells caused such cells to accumulate in inflamed lungs." (PMID 38037190, 2023). "We similarly applied this strategy to data from IL-4-stimulated human and NHP whole blood cells, and compared them to human influenza viral challenge blood cells." (PMID 36624212, 2023). "QQXD can reduce the expression of IL-1α, IL-4, IL12(P70), and TNF-α inflammatory factors in influenza mice, and prevent the excessive inflammatory reaction from aggravating lung injury." (PMID 36313993, 2022). "In absence or in the presence of low levels of influenza-induced IL-4, treatment with PPARγ agonist, Pioglitazone (PGZ), enhances M2 macrophage polarization and reduces influenza-induced lung disease." (PMID 36052067, 2022). "We found that IL-4 derived from TFH cells was necessary for efficient GC formation and for widening the breadth of influenza-specific antibody responses." (PMID 34145279, 2021). "It has been reported that influenza infection strongly promotes NKT cells-cytokine production, inducing an increase in the percentage of IFN-γ+ and IL-4+NKT cells, in mice." (PMID 32463330, 2020). "We were particularly interested in IL-2, IL-12p70, IFN-γ, IL-1β, IL-10, IL4, and TNF-α, given their involvement in the immune response during influenza infection and also given the phenotype of the response upon vaccination." (PMID 28792466, 2017). "The GPI-0100 dose was negatively correlated with the number of influenza-specific IFNγ- and IL17-producing T cells and positively correlated with the number of IL4-producing T cells observed after immunization and challenge." (PMID 28749414, 2017). "As expected (and in line with chemokine receptor expression) influenza-specific CD4+ T cells expressed mainly IFN-γ, along with very low but detectable levels of IL-4 and IL-17." (PMID 27571776, 2016). "After influenza vaccination, healthy volunteers showed a significant increase in the frequency of H1N1-specific IL-4+CD4+ T cells after vaccination." (PMID 26641243, 2015). "Both IL-4 and IFN-γ producing influenza-specific cell numbers peaked as early as 7 days in the EGFRI/vaccine group reaching 3-fold and 5-fold differences respectively when compared to the vehicle/vaccine control numbers (p < 0.001)." (PMID 26227481, 2015). "Although the role of IL-4 during influenza infection remains debatable, SOCS1−/−IFN-γ−/− mice showed increased IL-4 production following influenza infection." (PMID 25500584, 2014). "The comparable proportions of IL-4- and IFN-γ-secretors among the virus-specific CD4 T cells in DR1 mice was surprising and inconsistent with the Th1-polarized response expected after influenza infection." (PMID 22457834, 2012). "Pandemic influenza vaccines should preferentially activate both Th1 (IL-2, IFN-γ and TNF-α) and Th2 subsets (IL-4, IL-5, and IL-10) of T helper cells, since both are important for elimination of influenza virus from the host." (PMID 22069479, 2011). "Next the effects of DEP prior to infection with influenza in OVA-sensitized mice on the expression of inflammatory cytokines were examined, with a specific focus on TH2 cytokines, including IL-13 and IL-4." (PMID 19682371, 2009). "Immunization with these nanoparticles induced significant antigen-specific humoral (neutralizing antibodies) and cellular responses (IFN-γ and IL-4-secreting cells and NP147–155 tetramer-specific CTL responses) and conferred heterosubtypic influenza protection." (PMID 39452110, 2024). "In the pathway analysis, inflammatory-immune disease (e.g., IBD, influenza, and RA) and the related pathways (e.g., the IL-17 signaling pathway, the NOD-like receptor signaling pathway, interleukin-4 and interleukin-13 signaling, and signaling by interleukins) were enriched among the AFgenes." (PMID 39742001, 2024).
influenza (continued). "In each of the models, CD4+ T cells are recruited to the site of inflammation, and each type of infection is dominated by the corresponding TH cell subset, in numbers and proportions; Influenza by TH1 cells (IFNγ), N. brasiliensis by TH2 cells (IL-4, IL-13), and A. fumigatus by TH17 cells (IL-17)." (PMID 37696824, 2023). "In vivo administration of IL-4 and an anti-IL-4 antibody complex (IL-4C) increased CXCR3 expression in both memory and naïve phenotype CD8 T cells in the absence of antigenic stimulation, and protected mice from lethal influenza infection." (PMID 38037190, 2023). "This is also in agreement with the low production of IL-4 during early influenza infection, and thus, a lack of STAT6-dependent induction of Pparg gene." (PMID 36052067, 2022). "Additionally, enhanced systemic IL-4 levels in infected pregnant mice 10 DPI suggests potential for ongoing type-2 adaptive immune stimulation, which has been reported to exacerbate influenza infection." (PMID 32922392, 2020). "Expression of CD1d on macrophages, but not on B cells, is required to elicit IL-4 production by iNKT cells, and mice lacking macrophages or IL-4 develop fewer germinal centers and less influenza specific IgG1 than wild-type mice." (PMID 30369933, 2018). "In striking contrast, NKT cells represent up to 50%–70% of the total IL-4+ cells after influenza infection; however, we did not detect NKT cell production of other type 2 cytokines, such as IL-5 and IL-13." (PMID 29249358, 2018). "Interestingly, influenza infection not only results in an upregulation of activation markers but also in a robust production of IFN-γ and IL-4, with a similar percentage of NKT cells producing either cytokine." (PMID 29249358, 2018). "In order to investigate whether immunization with the different influenza vaccines induced cell-mediated immune responses, the antigen-specific frequencies of both IFN-γ and IL-4 (B) cytokine producing splenocytes of immunized mice were assessed." (PMID 24671048, 2014). "To control for B cells being not generally impaired in their ability to perform Ig class switching caused by an IL‐5‐vaccine‐induced lack of IL‐5 and a consequently interlinked lack of IL‐4, we investigated the ability of IL‐5‐vaccinated horses to respond to a seasonal influenza vaccine." (PMID 40838325, 2025). "While IL-4–deficient mice have been shown to have an impairment in controlling influenza and other infections due to a reduction in CD8 T cell involvement, the virus level was not changed in our studies, supporting a primarily immunoregulatory role of IL-4 here." (PMID 40854598, 2025). "On IL-4 stimulation, we saw an upregulation of Ki-67 in human CD4 T cells but not NHP cells, much akin to IFNγ stimulation, and high expression of pSTAT3 in the natural killer of IL-4-stimulated blood cells, but not in PBMCs from humans challenged with influenza." (PMID 36624212, 2023). "IL-4 injection alone did not protect mice from lethal influenza." (PMID 38037190, 2023). "Cytokines such as IL-4, IL-5, IL-6, IL-8, IL-13, and TNF-α, chemokines such as CCL2 and CCL3, and the MC proteases tryptase and chymase can be detected in the supernatants of influenza infected MC cultures and in the bronchioalveolar lavage fluid (BALF) of both influenza patients and infected mice." (PMID 33680987, 2021). "However, the human CD4 T cell response to influenza is mainly a Th1 response, with no IL-4+ or IL-17+ cells detectable in the influenza specific 2+γ- population." (PMID 24788814, 2014). "In addition Th2-type cytokines, such as IL-4 and IL-13, and markers of eosinophil chemotaxis, such as CCL11 and CCR3, were increased in OVA-sensitized mice exposed to DEP prior to infection with influenza." (PMID 19682371, 2009).
influenza (continued). "Our study showed that Th1-type (IFN-γ) and Th2-type (IL-4) cytokine responses specific to HA1 were significantly induced, which may have contributed to broadening the protection efficiency of our vaccine candidate pSIP401-HA1-ZN-3 against divergent influenza subtypes." (PMID 36085207, 2022). "However, despite the polarization towards a Th2 phenotype, IL-13 levels were not different in this model (data not shown) suggesting that DE enhanced influenza infection may specifically increase Th2 cytokines induced in influenza such as IL-4." (PMID 21092162, 2010). "Evidence suggests an increased Th2 response or presence of Th2 cytokines impairs anti-influenza immunity; mice treated with IL-4 do not have efficient CD8+ T cell activation and clear influenza infection slower than untreated controls." (PMID 32974217, 2020). "Following 12 h ex vivo stimulation with the LACK158–173 peptide, a distinct LACK158–173+CD4+ T cell population in the spleens of vaccinated mice produced IFN-γ, but no IL-4 (data not shown), indicating that LACK158–173 vaccination in the context of influenza induces a Th1-bias." (PMID 22470440, 2012). "However, the lack of difference in IL-4 and IFNγ production could be attributed to the lack of strong CD4+ or CD8+ T cells epitopes in influenza HA protein in C57BL/6 mice that is restricted by H-2b47." (PMID 27404789, 2016).